TRAF2 (TNF receptor associated factor 2)
Diseases named in the same sentence as TRAF2 in open-access papers (continued):
Sharing a sentence is not in itself a finding about the gene and the disease.
cancer (continued). "We conduct more in-depth studies on the biological functions of TRAF2 in various types of cancers." (PMID 40144665, 2025). "Considering the activity of TRAF2 in keeping the balance between Tregs and effector T cells (Teffs), TRAF2 could display a role in facilitating cancer immune evasion." (PMID 40229245, 2025). "From a pan-cancer perspective, TRAF2 was increased in multiple cancer types, including PCa." (PMID 40560737, 2025). "In cancer, TRAF2 activates NF-κB to drive inflammation, angiogenesis, and immunosuppressive TME." (PMID 40229245, 2025). "Additionally, we outline potential therapeutic strategies, including candidate inhibitors and combination approaches, and highlight future research directions to deepen the knowledge on TRAF2’s pivotal role in cancer biology." (PMID 40229245, 2025). "Immunofluorescence analysis showed that rapamycin treatment in TRAF2 knockout group significantly increased the co‐localization of cancer cells with macrophages compared to TRAF2 knockout or rapamycin group, suggesting that TRAF2 knockout increased phagocytosis in response to rapamycin." (PMID 39665172, 2025). "Targeting TRAF2 or TRAF2-dependent signaling pathways might represent a promising anti-cancer therapeutic strategy." (PMID 40229245, 2025). "Additionally, TRAF2 enhances the immunosuppressive functions of MDSCs in tumors, establishing its position as a key mediator of immune homeostasis and cancer immune evasion." (PMID 40229245, 2025). "Suppression of TRAF2 in these cancer cells results in NF-κB downregulation and apoptosis." (PMID 40229245, 2025). "Previous studies were conducted on TRAF2 in some cancer types." (PMID 40144665, 2025). "The epigenetic alterations in TRAF2 was significant across various types of cancers." (PMID 40144665, 2025). "In addition, we applied the GEPIA2 database to investigate the expression of TRAF2 in different cancer stages." (PMID 40144665, 2025). "TRAF2 could have a role in the development and aggressiveness of cancer cells by influencing the differentiation into Th17 cells, which exerts immunosuppressive functions and stimulates angiogenesis by secreting IL-17." (PMID 40229245, 2025). "TRAF2 was identified as an oncogenic factor in several cancers." (PMID 38825674, 2024). "Dysregulated expression of TRAF2 has been reported in a variety of human cancers." (PMID 37081115, 2023). "TRAF2 is involved in various cancer-relevant cellular processes, such as the activation of transcription factors of the NFκB family, stimulation of mitogen-activated protein (MAP) kinase cascades, endoplasmic reticulum (ER) stress signaling, autophagy, and the control of cell death programs." (PMID 36011046, 2022). "15d-PGJ2 has anti-cancer action via inhibiting eIF4A, reducing translation, and sequestering TRAF2." (PMID 35004322, 2021). "In cancers, TRAF2 and TRAF3 expressions are different depending on cancer types." (PMID 34257589, 2021). "Increased TRAF2 expression is recognized as a prognostic factor in several cancers." (PMID 31130821, 2019). "The exact roles of TRAF2 may be dependent on the genetic alteration context and malignant stage of the cancer cells as well as the nature of the environmental cue and treatment regimen." (PMID 30294322, 2018). "Functional contribution of these TRAF2 fusions to cancer pathogenesis is currently unclear." (PMID 30294322, 2018). "Importantly, suppression of TRAF2 in cancer cells harboring a TRAF2 copy number gain inhibits proliferation, NF-κB activation, anchorage-independent growth, and tumorigenesis." (PMID 30294322, 2018). "Thus, TRAF2 is required for the maintenance of the malignant state in certain cancer cells containing TRAF2 amplification or overexpression, and TRAF2 protein levels also regulate the sensitivity of cancer cells to chemotherapy and radiotherapy." (PMID 30294322, 2018).
cancer (continued). "Truncation and fusion of TRAF2 are relatively rare but also detected in human cancers." (PMID 30294322, 2018). "Another NFκB gene we investigated was TANK (also known as TRAF2), which is a critical upstream component in the NFκB activation pathway and therefore could be a factor that relates to inflammation as well as cancer development and progression." (PMID 23634849, 2013). "In rare cases, TRAF2 might be beneficial for cancers since it displays an anti-tumoral activity." (PMID 40229245, 2025). "Besides this, TRAF2 seems to mediate EMT induced by low oxygen levels in this cancer type." (PMID 40229245, 2025). "Therefore, TRAF2 is a putative SphK/S1P target during the cancer immune evasion." (PMID 38698424, 2024). "Our data indicate that TRAF2 and TRAF3 frameshift mutations and their regional difference as well as altered expressions are present in MSI-H CCs, which could contribute to MSI-H cancer development." (PMID 34257589, 2021). "However, it is not well known whether genes with dual TSG and oncogene properties such as TRAF2 and TRAF3 frequently harbor inactivating mutations in cancers with MSI-H." (PMID 34257589, 2021). "Therefore, the function of USP17 in enhancing inflammation and stemness in cancer cells may result from its ability to bind and disrupt the TRAF2/TRAF3 complex." (PMID 30038267, 2018). "Thus, the currently demonstrated CD147-regulated TRAF2 and its downstream signaling pathways in spermatogenesis may have broader implications in cancer biology and oncotargets." (PMID 27902973, 2017). "In addition, the quantitative loss of TRAF2-associated cIAP1 following bivalent IAP antagonist treatment correlated with inhibition of TNF-stimulated p65/NF-κB nuclear translocation and gene transcription in the cancer cell lines tested." (PMID 28149532, 2017). "The intracellular S1P, on the other hand, promotes cancer progression in a receptor-independent manner, by either mediating calcium release from endoplasmic reticulum, or by interacting with its intracellular targets, such as HDAC and TNF receptor-associated factor 2 (TRAF2)." (PMID 25330231, 2014). "We explored the relationship between TRAF2 expression and OS, DSS, and PFI in 33 cancer types by TCGA RNA-seq and clinical data." (PMID 40144665, 2025). "Since the binding of CD47 on cancer cells to SIRPα on macrophage results in inhibition of macrophage phagocytosis, bioinformatic analysis using TISIDB database suggests that TRAF2 expression is negatively correlated with macrophage abundance in LUSC." (PMID 39665172, 2025). "Combined TRAF2 and cIAP1/2 inhibition improved immune checkpoint blockade (ICB) efficacy in mouse cancer models." (PMID 40229245, 2025). "Modulating TRAF2 expression or activity can influence downstream TNFR signaling and is emerging as a promising cancer therapy target due to its pro-tumoral role." (PMID 40229245, 2025). "Specifically, TRAF2, TRAF4, and TRAF7 are generally overexpressed in a pan-cancer context, and high expression levels of these genes are associated with poorer patient prognosis." (PMID 38825674, 2024). "TRAF2 is an oncogenic protein involved in resistance to anoikis and TNF-mediated apoptosis in cancer cells via NFκB." (PMID 38184997, 2024). "This analysis revealed that TRAF1, TRAF2, TRAF3, TRAF4, TRAF6, and TRAF7 exhibit higher expression levels in cancer tissues, whereas TRAF5 is expressed at lower levels in these tissues." (PMID 38825674, 2024). "The TNFR2/TRAF2 axis is responsible for co-stimulation of CD8+ T cells, which sensitize cancer cells to cytotoxic effects." (PMID 38698424, 2024). "This stable tRNA has a substantially increased efficiency necessary to support a pro‐cancer translation program including c‐Myc, BCL2, RAB31, JUNB and TRAF2." (PMID 37983928, 2023). "Traf2 and Nck-interacting kinase (TNIK) is known for its regulatory role in various processes within cancer cells." (PMID 38264262, 2023).
cancer (continued). "Traf2 and Nck-interacting serine protein kinase (TNIK) are cancer target proteins that are overexpressed in mammary cancer cells and contribute to the progression of cancer." (PMID 37446730, 2023). "TRIM37 has been reported to interact with TRAF2 and TRAF6 to promote cancer cell proliferation and chemoresistance." (PMID 35163097, 2022). "From our results, we first identified the roles and underlying mechanisms of MSI1 and miR-671-5p in GBM, which regulate radioresistance by STAT3 inhibition and cancer migration and CSC function by TRAF2 suppression." (PMID 35052701, 2021). "The addition of TRAF2 to the DYRK1A–SPRY2–EGFR axis has broadened the complexity of regulation of EGFR and its dynamics in cancer signaling." (PMID 34117217, 2021). "In the cancers, MSS (41%, 28/68 CCs) and MSI-H (39%, 39/100 CCs) CCs showed positive TRAF2 immunostaining in cancer cells." (PMID 34257589, 2021). "The TRAF2 mutation (p.Pro9LeufsX77) identified in the present study would result in production of only a short protein with 8 amino acids without any of the domains, which might lose the activities or be degraded by nonsense-mediated mRNA decay that is frequently present in MSI-H cancers." (PMID 34257589, 2021). "The current computational study was conducted to identify phytotherapeutic compound for inhibition of proliferation function in cancer cells through inhibiting the activity ofmutated CFLAR and TRAF2 function." (PMID 34602774, 2021). "In the last decade, Traf2- and Nck-interacting kinase (TNIK) has been reported as a first-in-class cancer target molecule." (PMID 32810161, 2020). "TRAF2 is similar to TRAF6 and plays an important role in inflammation, immune response, and malignant tumor infiltration." (PMID 33456463, 2020). "Our findings support the proposal that β-carotene has anti-cancer activity by reducing NADPH oxidase-mediated production of ROS, NF-κB activation and NF-κB-regulated TRAF1 and TRAF2 gene expression, and hyper-proliferation in AGS cells." (PMID 31835889, 2019). "USP4 has previously been confirmed to target TRAF2 and TRAF6 for deubiquitination and it has been established that USP4 inhibits TNFα-induced cancer cell migration." (PMID 30194441, 2018). "Interestingly, it has been reported that CD147 could bind to TRAF2 for enhancing cancer metastasis." (PMID 27902973, 2017). "Collectively, we suggest that AMG655-induced DR5 activation promotes TRAF2 degradation accompanied with a suppression of polyubiquitinaiton and JNK signaling, resulting in eventual suppression of cancer cell invasion." (PMID 28482915, 2017). "In cluster 2, the key genes CDKN2A, HSP90AB1, TRAF2 and RAF1 are effective agents in cancer pathway." (PMID 29379595, 2017). "The current study has demonstrated that S1P-dependent TRAF2 polyubiquitination, downstream of caspase-8, is important for mediating DR5 suppression-induced promotion of cancer cell invasion." (PMID 28482915, 2017). "We here demonstrate that NBD compounds, already known to inhibit both the catalytic and TRAF2/JNK1-sequestering activity of GSTs and to trigger cell cycle arrest and apoptosis in cancer cells, share the ability to act as late-phase autophagy inhibitors." (PMID 26847645, 2016). "Traf2- and Nck-interacting kinase (TNIK) has recently been considered as a first-in-class anti-cancer target molecule to regulate Wnt signaling pathway, but pharmacologic inhibition of its EMT activity has not yet been studied." (PMID 25337707, 2014). "Cancer cells that have been “primed” with TWEAK are sensitized to TNFα-induced cell death owing to the depletion of cIAP1 and TRAF2 proteins." (PMID 24550918, 2014). "Recent reports have proposed the Traf2- and Nck-interacting kinase (TNIK) as a first-in-class anti-cancer target molecule." (PMID 25337707, 2014). "Our analysis showed that AATF, LGALS3, and SRC are up regulated in 8/13 of cancer models, and CDC2L2, E2F6, LGALS9, PDCD8, RELB, TRADD, and TRAF2 in 7/13." (PMID 19402918, 2009).
cancer (continued). "TRAF2 is a critical signaling hub involved in modulating pathways downstream of TNFR1 and TNFR2, influencing cell survival, apoptosis, inflammation, immune regulation, and cancer progression." (PMID 40229245, 2025). "Significantly, by combining our previous research with the construction of chemoresistant PC cell lines, the perplexing protein interactions between CDCA3 and NF-κB a cancer-related signaling pathway were illustrated in present study, that is CDCA3/TRAF2/NF-κB axis." (PMID 40822457, 2025). "Additionally, TNF-like weak inducer of apoptosis (TWEAK), a ligand of Fn14, also makes cancer cells more vulnerable to TNF-mediated killing, supporting Fn14’s role in depleting cytosolic TRAF2-cIAP1/2 complexes." (PMID 40229245, 2025). "Besides, previous studies have shown that TNFSF10 can induce autophagy through the MAPK8 activation pathway of TRAF2 and RIPK1, which in turn blunts the apoptosis of cancer cells." (PMID 38375157, 2024). "Since TRAF2, IKBKB, and TAB2 proteins are directly or indirectly involved in NFκB activation, the influence of these proteins on tumorigenesis is discussed in many studies related to cancer occurrence." (PMID 39061149, 2024). "TRAF2 and TRAF7 showed high protein levels in all cancer cell lines, except for the MeWo cells." (PMID 37389738, 2023). "In BET bromodomain inhibitor JQ1‐resistance HCT116 cells, which showed high resistance to various anti‐cancer drugs, including cisplatin, TNIK (TRAF2 and NCK‐interacting protein kinase) was a regulator of Wnt/β‐catenin signaling and transactivate cyclin D1 (CCND1) and cyclin E1 (CCNE1)." (PMID 36408691, 2023). "TRAF2: Most normal cells showed negative to weak cytoplasmic positivity with both antibodies, whereas cancer tissues showed strong cytoplasmic positivity." (PMID 36012427, 2022). "TRAF2 and TRAF3 reveal both activities (i.e., cell death and survival) and thus finding gene alteration status in a specific cancer type is important for the understanding cancer-related functions of TRAF2 and TRAF3." (PMID 34257589, 2021). "Traf2- and Nck-interacting kinase (TNIK) has recently been considered as an anti-proliferative target molecule to regulate the Wnt signaling pathway in several types of cancer cells." (PMID 32810161, 2020). "The current study continues our previous exploration of the critical role of TRAF2-dependent enhancement of cancer cell invasion and metastasis induced by DR5 suppression to further understand the mechanism by which TRAF2 is activated during DR5 suppression-induced promotion of cancer cell invasion." (PMID 28482915, 2017). "Our data indicates that the TRAF2/NIK/NF-κB2 pathway regulates PDAC cell tumorigenicity and could be a valuable target for therapy of this cancer." (PMID 23301098, 2013). "Other mechanisms by which SGs prevent cancer cell resistance to bortezomib might involve the sequestration and inactivation of key apoptotic signaling molecules such as RACK1 or TRAF2, thus preventing the initiation of apoptotic cascades." (PMID 20429927, 2010). "TRAF2 represents a negative prognostic factor, which is required for the malignant phenotype, anchorage-independent growth and increased resistance to chemotherapy and radiotherapy of several cancers." (PMID 40229245, 2025). "In this sense, the TRAF2 and TRAF3 mutations might inactivate their activities, but their biological functions and contributions to cancer development are not explored in our study and should be further studied." (PMID 34257589, 2021). "Hence, it is likely that TRAF2 may play a critical role in the regulation of the survival and metastasis of TRAIL-resistant cancer cells." (PMID 33810241, 2021).
cancer (continued). "In agreement with our previous finding that caspase-8 enzymatic activity is not required for mediating DR5 suppression-induced cancer cell invasion, the current study further demonstrates that caspase-8 mediates TRAF2 polyubiquitination induced by DR5 suppression independent of its caspase activity." (PMID 28482915, 2017). "Moreover, the downstream effectors of KHDC4 and TRAF2 were observed to be positively correlated with E2F4, suggesting that E2F4, in addition to affecting KHDC4 and TRAF2 directly, indirectly influences their downstream regulators to participate in cancer malignancy." (PMID 40560737, 2025). "Available FADD and caspase-8 may recruit and stabilize TRAF2 (and perhaps other unknown proteins), resulting in the activation of ERK and JNK signaling and subsequent AP-1-dependent expression and activation of MMPs (e.g., MMP1) and final promotion of invasion and metastasis of cancer cells." (PMID 26510914, 2015). "In other cancers where melatonin activates the PERK axis, increased expression of IRE1α or p‐IRE1α expression has also been observed; however, TRAF2 or XBP1s expression were not assessed." (PMID 40873119, 2025). "The protein levels of TRAF2 and TRAF6 were reduced in cancer cell lines treated with NA, but not TRAF3, TRADD, and FADD." (PMID 25575821, 2015).